RN7SKP15 (RN7SK pseudogene 15)
Gene: Miscellaneous RNA gene on chromosome 12 (27,806,082 to 27,806,390, reverse strand). Ensembl gene ENSG00000201612.
Homologues: Orthologues: chimpanzee 7SK (98% identical). Paralogues in human: RN7SKP203 (76% identical), RN7SKP255 (75% identical), RN7SKP71 (75% identical), 7SK (74% identical), RN7SKP95 (74% identical), RN7SKP176 (74% identical), RN7SKP9 (74% identical), RN7SKP80 (74% identical), RN7SKP237 (73% identical), RN7SKP25 (73% identical), RN7SKP79 (73% identical), RN7SKP204 (73% identical), and 284 more.